APOE (apolipoprotein E)
Diseases named in the same sentence as APOE in open-access papers (continued):
Sharing a sentence is not in itself a finding about the gene and the disease.
neurological diseases (continued). "Several other apoE-based peptides for neurologic diseases are actively being developed and have recently been reviewed." (PMID 33800446, 2021). "The activation of the PM20D1/N-acyl amino acid pathway is suggested as a contributor to the protection from metabolic and neurological diseases observed in APOE-KO mice." (PMID 33298155, 2020). "Mimetic peptides derived from the receptor-binding or lipid-binding regions of APOE have been developed and tested for neurological diseases including AD." (PMID 32899606, 2020). "Similar to COG1410, the peptide COG112 was derived from amino acids 133-149 of the receptor-binding region of APOE, which has been shown to be anti-inflammatory in mouse models of neurological disease." (PMID 32899606, 2020). "In this Review, we revisit the different aspects of APOE involvement in neurodegeneration and neurological diseases, with particular attention to sex differences in the contribution of APOE to LOAD susceptibility." (PMID 32859588, 2020). "The genes of the violet module identified in AD APOE ε4 carriers were enriched in hereditary disorders, neurological diseases, psychological disorders, and nervous system development and function." (PMID 27462267, 2016). "Based on functional similarities between clusterin and ApoE, the association between ApoE isoforms and WD onset, and the role of clusterin in copper-ATPase degradation, these molecules potentially could play a role in modifying the expression of neurological disease such as AD, MD, and WD." (PMID 23986700, 2013). "Several studies have suggested that the structural and biophysical properties of apoE can dictate the function of the protein and have provided insight into the mechanisms by which apoE is involved in cardiovascular and neurological diseases." (PMID 22069485, 2011). "We tested the effects of injected apoE-mimetic peptides with known neuroprotective activity in different animal models of neurological diseases." (PMID 19997607, 2009). "Moreover, therapeutic strategies targeting APOE have emerged as a promising approach for treating both cardiovascular and neurological diseases." (PMID 40699836, 2025). "ApoE is involved in various activities including lipid transport, synaptic growth and neuroplasticity, and has been shown to play an important role in a variety of neurological diseases." (PMID 38545108, 2024). "Apart from its role in ASCVD, ApoE also exhibits significant effects on neurological diseases." (PMID 38429638, 2024). "Thus, it would be interesting to further define the molecular mechanisms by which apoE regulates neuronal fate, providing insight into the roles of apoE isoforms in AD and other neurological diseases." (PMID 37605285, 2023). "By illustrating how apoE isoforms differentially regulate microglial function, our study sheds light on the therapeutic premise of strategies that target the microglia-mediated responses for treating neurological diseases." (PMID 36419137, 2022). "As a result, APOE ɛ4 acts directly or in concert with age, head injury, oxidative stress, ischaemia and inflammation to alter disease onset, progression and prognosis in a variety of neurological disorders." (PMID 32954261, 2019). "However, by the mid-1980s, it had become apparent that apoE also plays significant roles in neuronal repair and remodeling as well as in neurological disease." (PMID 31186040, 2019). "Apolipoprotein epsilon 4 (APOE-ε4) associates with many neurologic diseases, and consensus on the ε4 allele as a risk factor is lacking." (PMID 30223506, 2018). "There are numerous reports surrounding ApoE in the context of neurological disorders." (PMID 25919366, 2014). "Furthermore, targeted replacement (TR) mice that possess the human ApoE isoforms substituted into the mouse gene locus have become popular tools for studying the effect of ApoE on the pathogenesis of neurologic diseases." (PMID 22675504, 2012).
neurological diseases (continued). "Ultimately, an understanding of the regulation of CSF apoE levels could lead to novel apoE-based treatments for AD and other neurological disorders." (PMID 17430597, 2007). "For example, the enrichment of ApoE residues in the graphene-based materials corona could facilitate the traversal of the blood-brain barrier and enable targeting of the cerebrovascular endothelium for the treatment of neurological diseases." (PMID 37568181, 2023). "APOE*ε2 may also modify the risks of other less common neurological disorders." (PMID 33148290, 2020). "Moreover, accumulating studies have demonstrated that APOE mimic peptide could reduce apoptosis and neuroinflammation in many neurological diseases." (PMID 29875635, 2018). "Furthermore, the glutamate decarboxylation product, the brain inhibitory neurotransmitter gamma aminobutyric acid (GABA), is also present at low levels in KO cells, which overlaps with population census results and may provide new insights into the role of ApoE genes in neurological disorders." (PMID 36139057, 2022). "Previous studies also suggest that structure correctors are considered as a potential therapeutic approach to reduce ApoE ε4 pathology in both CVD and neurological disorders, including AD." (PMID 35011591, 2021). "Additionally, upregulated APOE is characteristic of DAM and MGnD in the CNS, implicating innate immune involvement in various neurological disorders." (PMID 40051633, 2025). "This is likely explained by the absence of neurologic diseases in the data set, or that APOE-ε4 carriers only represent 30% of the sample, resulting in a reduction in statistical power." (PMID 40829101, 2025). "The aim of this work was to present the current understanding of APOE involvement in the pathophysiology of neurological disorders, highlighting its role as a non-protagonist actor." (PMID 39596597, 2024). "While apoE isoform-specific interactions with Aβ peptides likely contribute to the stratification of AD by APOE, the mechanisms by which apoE isoforms may influence the clinical outcomes of these several other neurologic diseases is not at all clear." (PMID 16934151, 2006). "We hypothesized that, in this cohort of older adults without neurologic disorders, higher WMHVR would be related to increased HAR, and that this relationship would be partly dependent on levels of mid-life CVRF but independent of Aβ levels and APOE-ε4 status." (PMID 40829101, 2025).
metabolic disorders (79 papers, 2011 to 2026). "Together, these findings pave the way for novel strategies to a holistic targeting of metabolic disorders using precision-engineered variants of APOE." (PMID 41354325, 2025). "Our study demonstrates that ZXYF alleviated HFD caused intestinal barrier damage and cholesterol metabolism disorders by maintaining gut microbiota homeostasis and gut microbiome metabolism in ApoE−/− mice." (PMID 40414923, 2025). "Perturbations of ApoE can result in several metabolic disorders and ApoE genotypes have been associated with multiple diseases." (PMID 37506130, 2023). "In line with this metabolic disorder, S. mansoni-infected male Apolipoprotein E deficient (ApoE-/-) mice on high-fat diet (HFD) modulates oxygen consumption on bone marrow myeloid progenitors, culminating in Ki-67 expression and expansion of GMP." (PMID 36263057, 2022). "Apolipoprotein E-deficient (apoE-/-) mice (C57 genetic background) are considered to be the ideal animal model for human lipoprotein disorders and AS studies." (PMID 33816331, 2021). "Apolipoprotein E-deficient (ApoE-/-) mice represent a good model to study cardiovascular and lifestyle-related metabolic diseases." (PMID 30818779, 2019). "APOE genetic variants have been associated with several metabolic disorders including high obesity risk." (PMID 29795275, 2018). "Overall, these data have shown that the gut dominant microbiota have changed after knockout of ApoE-deficient and obese leptin-deficient, which may be closely associated with metabolic diseases." (PMID 36337626, 2022). "Overall, these data have shown that the key metabolites in intestinal microorganisms of ApoE-deficient and obese leptin-deficient mice with metabolic diseases may play causal roles in the pathophysiology of metabolic diseases." (PMID 36337626, 2022). "Other therapeutic effects of GA could be anticipated in lipid and metabolic disorders associated with higher demand of ApoE activity or unfavorable APOE haplotypes." (PMID 32616652, 2020). "In addition to affecting lipo-protein function and subsequent cardio-metabolic diseases, the ApoE e4 allele moderates macrophage pro-/anti-inflammatory phenotypes." (PMID 33092637, 2020). "Therefore, it can be concluded that lipid and lipoprotein disorders in CKD should be analyzed considering APOE gene polymorphism." (PMID 30851738, 2019). "Notably, soluble MULT1 (sMULT1) is present at high levels in the serum of ApoE−/− mice, which are prone to develop metabolic disorders associated with liver inflammation." (PMID 28128200, 2017). "Further, Eln+/−; ApoE−/− mutants have significant impairment of insulin sensitivity by insulin tolerance testing, independent of body weight or diet, suggesting that elastin insufficiency predisposes to metabolic disease in susceptible individuals." (PMID 26167199, 2014). "Our results support a model by which ApoE compensates for the loss of ApoB function through transcriptional activation and post-translational modifications and provide new insights into how hepatic lipid content is regulated by ApoE, whose abnormalities are implicated in metabolic diseases." (PMID 40180213, 2025). "In this study, activated inflammation was observed to induce abnormal glucolipid metabolic disorders in the hepatic tissues of high-fat diet (HFD)-fed ApoE-/- mice." (PMID 38617550, 2024). "ApoE knockout (ApoE-/-) mice fed a high-fat diet are more prone to metabolic disorders in vivo than wild-type mice." (PMID 36999158, 2023). "Here, we aimed to unveil the mechanisms underlying the protective effects of FGF21 on NASH using APOE*3-Leiden.CETP mice, a well-established model for human-like metabolic diseases." (PMID 36648330, 2023). "ApoE−/− and ob/ob mice are widely used to study the pharmacology and pathogeneses of metabolic diseases." (PMID 36337626, 2022). "ApoE−/− and ob/ob mice are often used as animal models to study the pathogenesis of metabolic diseases." (PMID 36337626, 2022).
metabolic disorders (continued). "Although LPG is one of apoE related lipoprotein disorders, it affects predominantly in kidney and the histological features are dilated glomerular capillaries with lipoprotein thrombi." (PMID 32441489, 2020). "The different isoforms of the apolipoprotein E (APOE) are an important source of variability in metabolic disorders and influence the response to the pesticide chlorpyrifos (CPF)." (PMID 33383760, 2020). "The sensitivity of the male wildtype to the HFD/HSD as measured by alterations in cognitive function and functional connectivity suggested the risk factor was not ApoE ε4, but instead, a metabolic disorder." (PMID 39506641, 2024). "In line with our findings, previous evidence has shown that oxLDL and lipid peroxidation products trigger ER stress and the production of UPR, characterized by GRP78 localization in ApoE−/− mouse vascular cells and atherosclerotic lesions, and in the plasma of patients with metabolic disorders." (PMID 37138269, 2023). "Targeting the APOE–BCKD complex interaction could represent a novel approach for metabolic disease therapy and prevention." (PMID 36749362, 2023). "Further, the data demonstrate that APOE4 is associated with deleterious systemic and neural phenotypes and an altered response to a metabolic stressor, findings relevant to the understanding of interactions between the APOE genotype and risks for metabolic disorders." (PMID 36837905, 2023). "Therefore, under the conditions of ApoE gene knockout and a high-fat diet, the body can reduce the metabolic disorder of liver cholesterol by promoting the liver to excrete unesterified cholesterol into the bile duct or small intestine." (PMID 37061692, 2023). "It is also interesting to note that the expression of jun might also be affected by ApoE, further highlighting the increasingly recognized relationship of carcinogenesis and metabolic disorders." (PMID 23922661, 2013). "Notably, central genes (APP, MBP, and APOE) in the network are implicated in neuro-pathological disorders and metabolic disease, but have not previously been assigned significance in brain metastasis." (PMID 25593989, 2014). "This suggests that while APOE plays an essential role in lipid homeostasis under normal conditions, alterations in its expression or function may lead to lipid dysregulation, which could have significant implications for metabolic diseases such as hyperlipidemia and atherosclerosis." (PMID 41354325, 2025). "Therefore, the lack of functional ApoE have severe metabolic disorders, and the extremely rare ApoE-deficiency condition may be in accordance with the favourable selective pressure in humans." (PMID 25148848, 2014). "We conclude that APOE on VLDL modulates LPL activity and could be a relevant factor in the pathogenesis of metabolic disease." (PMID 34863862, 2022). "The ApoE gene may be crucial for storage of fat in the thigh since it limits LPL-mediated hydrolysis of triglycerides and LPL activity is positively correlated to thigh exercise which can raise metabolic rate and help with metabolic disease." (PMID 39598239, 2024).
heart disease (67 papers, 2010 to 2026). "Although APOE*4 is associated with adverse plasma lipid profile (high LDL-cholesterol, high ApoB, low plasma ApoE levels) and high risk of heart disease and AD, the effect of APOE*2 on these traits is in opposite direction." (PMID 34935119, 2022). "ApoE ε4 carriers presented higher risk of heart disease; Clock C-carriers were more frequently smokers than non C-carriers." (PMID 32485802, 2020). "Data from 136,701 patients were available to compare lipid biomarker levels across Omega-3 Index categories associated with heart disease risk in all APOE genotypes." (PMID 24595593, 2014). "We hypothesized that the APOE genotype and age-associated comorbidities, such as heart disease, are associated with unfavorable outcomes following TBI in older patients." (PMID 39628897, 2024). "We hypothesized that the APOE allelic variance and certain age-associated comorbidities, such as heart disease, are associated with unfavorable outcomes following TBI in older patients." (PMID 39628897, 2024). "Thus, we used CVDs-prone ApoE−/− mice to evaluate the potential adverse effect of DEP on animals with a predisposition for heart disease." (PMID 38114606, 2023). "Our studies suggested that human ApoE polymorphism is associated with heart performance, and could be a potential therapeutic target to prevent and treat heart diseases." (PMID 36766690, 2023). "The present experiments were designed to investigate the possible development of delayed cardiac disease after exposure to low and intermediate doses of ionizing radiation in wt-C57Bl6 and ApoE-deficient mice, to assess the contribution of the atherogenic co-morbidity factor." (PMID 23451141, 2013). "Firstly, it was previously reported that apoE enhanced cell lipid homeostasis and could reduce the risk of heart disease." (PMID 21549015, 2011). "It seems to be influenced by individual factors like a person’s sex, genetic makeup (especially the APOE gene), and other health conditions like heart disease." (PMID 41465790, 2025). "ApoE ε4+ patients have a higher proportion of history of heart disease than ApoE ε4− (8.70% vs. 0.00%, χ2 = 3.944, p = 0.047)." (PMID 32485802, 2020). "GDF11 decreases the risk of cardiovascular events and death in patients with stable ischaemic heart disease, protects against endothelial injury and reduces atherosclerotic lesion formation in apolipoprotein E-Null mice." (PMID 29113418, 2017). "The T-wave morphology, however, was a finding seemingly unique to models of cardiac disease, namely, the spontaneously hypertensive rat and the ApoE–/– mouse." (PMID 21524982, 2011). "We found that ApoE ε4 carriers had more frequent history of heart disease than ε4 non carriers." (PMID 32485802, 2020). "When adjusting for age, sex, education, smoking, drinking, intensity of physical activity, BMI, log-transformed FBG, MAP, pulse rates, and heart disease, MMSE scores positively correlated with serum HDL level (r = 0.217, df = 176, p = 0.004) but not with LDL, TG, or TC levels in APOE ε4 carriers." (PMID 32231559, 2020).